BCL2 (BCL2 apoptosis regulator)
Diseases named in the same sentence as BCL2 in open-access papers (continued):
Sharing a sentence is not in itself a finding about the gene and the disease.
renal carcinoma (continued). "In addition to HO-1 over-expression, c-Met-mediated increase in the expression of anti-apoptotic molecules, such as Bcl-2 and Bcl-XL, protects renal cancer cells from apoptosis." (PMID 28724911, 2017). "Furthermore, it has been recently shown that the downregulation of Bcl-2 sensitises IFN-resistant renal cancer cells to Fas." (PMID 17031406, 2006). "Renal Cancer; stimulate apoptosis in Caki cells via DNA fragmentation, the activation of cas-pase-3, cleavage of phospholipase C-g1, and the stimulation of ROS generation by the production of cytochrome c and downregulation of the Bcl2, Bcl-xL, IAP, and Akt pathways." (PMID 36712505, 2022). "In addition, the combined treatment with rosiglitazone and TNF-α-related apoptosis inducing ligand (TRAIL) could induce apoptosis in renal cancer cells via induction of Bcl-2 overexpression." (PMID 26694491, 2015). "To determine whether Bcl-2 and XIAP downregulation was a cause or a consequence of caspase activation and apoptosis, we treated A498 renal cancer cells with DMSO, AR-A014418, DEVD-CHO (reversible tetrapeptide inhibitor of caspase-3 and caspase-7) or a combination of AR-A014418 and DEVD-CHO." (PMID 19920820, 2009). "Notably, it has been shown that the steroidal alkaloid solamargine, which has a structural similarity to solanine, may cause caspase-dependent apoptosis by regulating the expression of Bcl-2/Bax and may possess anti-carcinogenic properties in human renal carcinoma cells." (PMID 39124760, 2024). "c-MET rescued apoptosis in renal cancer cells, and inhibition of c-MET signaling increased mitochondrial release of cytochrome C and the Bax/Bcl2 ratio." (PMID 28404966, 2017). "In renal cancer cells, our observation suggests that, HNK can promote cancer cell apoptosis through the down-regulation of c-Met-induced Bcl-2 and Bcl-XL expression, and through increased cleavage of caspase-3." (PMID 28724911, 2017). "In this study, we showed that in Caki-1 and 786-O renal cancer cells, STAT3 inhibitor WP1066 inactivated the STAT3 signalling pathway and induced apoptosis, accompanied by reduced Bcl-2 expression." (PMID 20461084, 2010). "Using western immunoblotting, we found that inhibition of GSK-3 resulted in a significant decrease in the expression of anti-apoptotic proteins Bcl-2 and XIAP in ACHN and Caki1 renal cancer cells." (PMID 19920820, 2009). "We observed that inhibition of GSK-3 results in decreased expression of NF-κB target genes Bcl-2 and XIAP and a subsequent increase in renal cancer cell apoptosis." (PMID 19920820, 2009). "Increased expression of Bcl-2 and XIAP anti-apoptotic molecules, NF-κB target genes, has an important function in renal cancer cell survival and chemoresistance." (PMID 19920820, 2009). "Here, we found that inhibition of GSK-3 suppresses NF-κB-mediated expression of Bcl-2 and XIAP leading to a decreased survival of renal cancer cells." (PMID 19920820, 2009). "In this study, we show that inhibition of GSK-3 suppresses NF-κB-mediated expression of Bcl-2 and XIAP leading to a decreased survival of renal cancer cells." (PMID 19920820, 2009).
renal carcinoma (continued). "Using real-time PCR, we found that inhibition of GSK-3 resulted in a marked reduction in the expression of NF-κB target genes Bcl-2 and XIAP, suggesting a downregulation of NF-κB transcriptional activity in renal cancer cells." (PMID 19920820, 2009). "Increased expression of Bcl-2 and XIAP anti-apoptotic molecules, NF-κB target genes, has an important function in renal cancer cell survival." (PMID 19920820, 2009). "Taken together, our results suggest that inhibition of GSK-3 suppresses the expression of NF-κB target genes Bcl-2 and XIAP, resulting in decreased survival of renal cancer cells." (PMID 19920820, 2009). "Increased expression of Bcl-2 and XIAP anti-apoptotic molecules, NF-κB target genes, has an important function in renal cancer cell survival and chemoresistance and resistance to immunotherapy." (PMID 19920820, 2009). "We previously reported that the RNase activity of MCPIP1 regulates the expression of apoptosis-related transcripts and that a lack of MCPIP1 RNase activity increases BCL-2 expression in renal carcinoma cells." (PMID 39815326, 2025). "A new insight into the role of EVO as a potential anticancer agent for treatment of human renal carcinoma via stimulated JNK- and PERK-mediated phosphorylation of the Bcl-2 protein leading to disruption of the mitochondrial membrane potential was provided herein." (PMID 27483435, 2016). "For example, RU-486, a GCR antagonist, is used for the treatment of several cancers, including breast, ovarian, and prostate, and glaucoma, and it has been shown to sensitize renal carcinoma cells to TRAIL-induced apoptosis through up-regulation of DR5 and down-regulation of c-FLIP(L) and Bcl-2." (PMID 24802641, 2014). "Our finding of nuclear accumulation of GSK-3β suggests the possibility that GSK-3β could positively regulate NF-κB-mediated transcriptional activation of Bcl-2 and XIAP in the nucleus of renal cancer cells." (PMID 19920820, 2009). "As GSK-3β has a positive role in expression of certain NF-κB-regulated genes, we investigated whether inhibition of GSK-3 affects NF-κB-mediated expression of Bcl-2 and XIAP in renal cancer cells." (PMID 19920820, 2009). "Next, we found that in renal cancer cells, overexpression of MKRN2 led to elevated β-Catenin phosphorylation and reduced β-Catenin protein expression, resulting in the attenuation of Wnt pathway that is marked by the down-regulation of signature genes (c-Myc, Cyclin D, Axin2, Bcl-2, MMP2, and MMP9)." (PMID 40959281, 2025). "Besides RU-486, a GR antagonist, is used for treatment of several cancers, such as breast, ovarian, prostate, and glaucoma, and has been shown to sensitize renal carcinoma cells to TRAIL-induced apoptosis through up-regulation of DR5 and down-regulation of c-FLIP(L) and Bcl-2." (PMID 23517603, 2013).
atherosclerosis (41 papers, 2013 to 2026). A disease characterized by the build-up of fatty material and calcium deposition in the arterial wall resulting in partial or complete occlusion of the arterial lumen. "Pharmacological inhibition of Nhe1 suppressed endotoxin-potentiated atherosclerosis and increased Bcl-2 expression in atherosclerosis-prone ApoE-deficient Apoe–/– mice." (PMID 31484936, 2019). "In addition, the pro-apoptotic protein Bax and atherosclerosis-associated cytokines (interleukin-1β, interleukin-6, and tumor necrosis factor-α) were significantly downregulated, whereas the anti-apoptotic protein Bcl-2 was upregulated." (PMID 35137664, 2022). "In bovine aortic endothelial cells, crocin increased the bcl‐2/bax ratio and expression and inhibited aortic endothelial cell apoptosis and atherosclerosis." (PMID 38419885, 2024). "This suggests that IL‐38 can inhibit the progression of atherosclerosis by reducing apoptosis through the Bcl‐2/Bax pathway." (PMID 38334236, 2024). "The previous study reported that the Bax and caspase 3 expressions were increased, while Bcl-2 expression was decreased in atherosclerosis plaque." (PMID 32611832, 2020). "The PI3K-Akt signaling pathway is involved in atherosclerosis by blocking blood flow and inhibiting the migration of fibroblasts and can suppress neuronal cell death and improve tau hyperphosphorylation by BCL2, GSK3B, and IGF1R." (PMID 32802132, 2020). "The administration of agomir-124 significantly increased the expression level of Bcl-2, while decreased the levels of Bax and caspase 3 in the atherosclerotic lesions from atherosclerosis model mice." (PMID 32611832, 2020). "Our study demonstrated a reduction of Bax and a promotion of Bcl-2 and cell viability by miR-30-5p, suggesting antiapoptosis effects of miR-30-5p on atherosclerosis." (PMID 31354385, 2019). "We also measured levels of COX2, VCAM1, CD68, SM22, Bcl2 mRNAs and of atherosclerosis/inflammation -related miRs 21-5p, 125a-5p, 126-5p, 146-5p, 155-5p and 424-5p, to compare the inflammation and apoptosis levels among plaque material." (PMID 28472949, 2017). "In ApoE (-/-) mice with HFD-induced atherosclerosis, the elevated expression of pro-apoptosis factors caspase-3, caspase-9 and Bax and the decreased level of anti-apoptosis factor Bcl-2 were induced by miR-210 overexpression." (PMID 28536634, 2017). "Results from previous studies found that Tan IIA decreased Bax protein level in atherosclerosis plaques and moderately increased Bcl-2 protein levels, and finally induced inhibition of atherogenesis." (PMID 28412716, 2017). "This is important because high levels of BCL-2 expression are essential to the atherosclerosis repair process orchestrated by endothelial cell activation." (PMID 25961846, 2015). "The downregulation of miR-34a could promote viability and inhibit apoptosis of ox-LDL-treated human aortic endothelial cells by upregulating Bcl-2, thus indicating a promising biomarker for atherosclerosis therapy." (PMID 33872218, 2021). "In rat atherosclerosis PCR array, Abca1, Bax, Bcl2, Bcl2a1, Cd44, Fabp3, Hbegf, Lypla1, Ptgs1, Selplg, Tgfb2, Tnc, and Vegfa had reverse trend between WT and MU groups, while the trends of Bcl2l1, Bid, Birc3, Cxcl1, Fas, Fn1, Itga2, Itga5, Lif, Nfkb1, Nr1h3, Ppard, and Sod1 were consistent." (PMID 34545275, 2021). "In addition, the expression levels of pro-apoptotic factors Bax and caspase 3 and anti-apoptotic factor Bcl-2 in atherosclerosis model mice were also examined using IHC assays." (PMID 32611832, 2020). "Based on the endothelial injury and repair mechanism, selective inhibition of BCL-2, the key-regulating gene for apoptosis-resistant endothelial cells, might be of therapy value for atherosclerosis." (PMID 25961846, 2015). "Overexpression of Bcl-2 could inhibit apoptosis of endothelial cells and thereby reduce the occurrence of atherosclerosis." (PMID 24319687, 2013).
atherosclerosis (continued). "IL‐38 has been shown to inhibit apoptosis by upregulating Bcl‐2 and downregulating Bax, thereby enhancing the survival of vascular endothelial cells, reducing the apoptosis of smooth muscle cells and macrophages in the fibrous cap, and finally attenuating atherosclerosis." (PMID 38334236, 2024). "After extracted genes in lipid and atherosclerosis pathway, a new PPI was established, which was prompted that genes including AKT1, BCL-2, CAPS3 and PPARG would be the core genes worked." (PMID 41559682, 2026). "The expression level of NDUFS3, E-cadherin, BCL2, P21 and SOX9 in atherosclerosis and chronic stress were lower than that in control group." (PMID 37642954, 2023). "Furthermore, a recent study suggested that miR-34a may be a promising target for the treatment of atherosclerosis as prevents cell growth and promotes apoptosis in atherosclerosis by regulating Bcl2, while deletion of miR-34a ameliorates atherosclerotic lesions in high-fat diet induced ApoE−/− mice." (PMID 35155600, 2021). "In STZ-diabetic mice, acacetin significantly upregulated the decreased signaling molecules (i.e. SOD, Bcl-2, PGC-1α, pAMPK, Sirt3 and Sirt1) in aorta tissue and attenuated atherosclerosis." (PMID 33519472, 2020). "In a mouse model of atherosclerosis, FHL3 was demonstrated to have anti-apoptotic effects in endothelial cells, through up-regulation of Bcl-2 via the PI3K pathway." (PMID 25860936, 2015). "Moreover, EOFAZ was found to upregulate Bcl-2 protein and mRNA levels and to attenuate ox-LDL-induced HAECs injury caused by apoptosis, revealing both its therapeutic potential for endothelial cell injury protection and its clinical application for atherosclerosis." (PMID 25610487, 2014). "The results showed that the EEDL exerted an anti-apoptotic effect by inhibiting the expression of Bax and enhancing the expression of Bcl-2, indicating that the anti-apoptotic effect of the EEDL may be one of the mechanisms to prevent atherosclerosis." (PMID 29896109, 2018). "Apoptosis in pathophysiology of atherosclerosis had indicated by powerful relevance between Bcl-2 protein and apoptosis in the progression of atherosclerotic, as well as the suppression of ox-LDL-abduced apoptosis through the Bcl-2 protein and Bax expression within human fatty streaks." (PMID 28878685, 2017).
endometriosis (41 papers, 2005 to 2026). The growth of functional endometrial tissue in anatomic sites outside the uterine body. "The variable expression of ER, PR, Bcl-2, and Ki-67 provide a basis for further studies on individualized hormonal medical treatment and for identifying aggressive forms of endometriosis with a high risk of recurrence." (PMID 40243611, 2025). "The different Bcl-2 gene expression, in the eutopic endometrium of women with endometriosis, caused reduced apoptotic cells and subsequently resulted in abnormal endometrial cells survival in the ectopic site." (PMID 39205918, 2024). "This work aimed to study the polymorphic variants of these proapoptotic and antiapoptotic genes, Bax -248G>A, rs4645878 and Bcl-2 -938C>A, rs2279115 SNPs, with endometriosis susceptibility in a sample of the Iranian population." (PMID 39205918, 2024). "We also reported about 3 times or greater risk of endometriosis when a combination of Bcl-2 -938C> A and Bax -248G> A were studied." (PMID 39205918, 2024). "This study investigates the relationship between polymorphic variants of Bax -248G>A and Bcl-2 -938C>A promoter regions with endometriosis risk in an Iranian population." (PMID 39205918, 2024). "The results suggest that the Bax -248G>A, rs4645878 and Bcl-2 -938C>A, rs2279115 single nucleotide polymorphisms play a significant role in the pathogenesis of endometriosis in Iranian women." (PMID 39205918, 2024). "Our data showed that the Bax -248G>A rs4645878 GG and, the Bcl-2 -938C>A rs2279115 AA were classified as adverse genotype combinations based on association with about 5 times higher risk of endometriosis." (PMID 39205918, 2024). "The frequencies of the mutant genotype AA and A allele carriers of Bcl-2 -938C>A polymorphism were approximately 4 and 2.5-fold higher in endometriosis compared to the control women, which were highly significant (p >0.001)." (PMID 39205918, 2024). "In the current study, we investigated the association of the SNPs in Bax and Bcl-2 genes, involved in apoptosis, with the risk of endometriosis." (PMID 39205918, 2024). "Stromal BCL2 levels are elevated in endometriosis and GWAS-identified sequence variants of BCL2 are associated with endometriosis." (PMID 37626707, 2023). "One of the miR-9-predicted targets is BCL2, a gene encoding an anti-apoptosis protein and were found to have higher expression in endometriosis patients." (PMID 36143357, 2022). "Two of them found that a higher Bcl-2 rate in endometriosis had a statistically significant association with more aggressive tumor behavior, starting from TE toward AE and finally cancers (both CCC and EnOC histotypes)." (PMID 35457244, 2022). "Furthermore, under the recessive model (AA vs. CC+CA), a significant difference of Bcl-2 -938C>A gene polymorphism with approximately 3-fold increase of endometriosis risk was observed." (PMID 39205918, 2024). "Furthermore, cases with the Bcl-2 -938C>A mutant A allele or AA variant and CA+AA vs. CC model exhibited an elevated risk of endometriosis." (PMID 39205918, 2024). "Furthermore, the combination effects of these 2 single nucleotide polymorphisms showed that women with Bax -248G>A GGand Bcl-2 -938C>A AA variant alleles were associated with about 5 times higher risk of endometriosis (p > 0.001)." (PMID 39205918, 2024). "Moreover, the allele A frequency of Bcl-2 -938C>A was associated with a 2-fold higher risk of endometriosis (p > 0.001)." (PMID 39205918, 2024). "On the other side, moderate/severe endometriosis risk was about 5 times greater in cases with Bcl-2 -938 C>A CA+AA genotype, which proposed that A allele might be a high-risk allele and could have a special effect on the severity of endometriosis disease." (PMID 39205918, 2024). "The results of our study provide evidence that Bcl-2 -938C>A and Bax -248G>A single nucleotide polymorphisms might be associated with the risk of endometriosis." (PMID 39205918, 2024).